BRAF (B-Raf proto-oncogene, serine/threonine kinase)
Diseases named in the same sentence as BRAF in open-access papers (continued):
Sharing a sentence is not in itself a finding about the gene and the disease.
melanoma (continued). "Although a direct mechanism involving BRAFV600E in the epigenetic silencing of RASSF1A has never been reported, RASSF1A hypermethylation has been found alongside BRAF (and NRAS) mutations, suggesting a synergistic effect of MAPK pathway mutations and the loss of RASSF1A on melanoma growth." (PMID 34066022, 2021). "This protective stromal signalling renders BRAF-mutant melanoma cells resistant to BRAFi treatment." (PMID 34067929, 2021). "Importantly, a subset of BRAF(V600E) melanoma patients (~20%) expressing the SMAD3‐signature was identified, suggesting that these tumors contained dedifferentiated melanoma cells with potential intrinsic resistance to BRAFi." (PMID 33724679, 2021). "Similarly, the RUNX1/CSF-1R/IL-34 axis was responsible for the tumor rebound in BRAF inhibitor resistant melanoma." (PMID 33408768, 2021). "ABMs can thus be used to simulate how drug-resistant tumour subclones (e.g. melanoma cells with elevated BRAF levels) and drug-sensitive tumour subclones evolve in time and space in response to various drug combinations, drug doses and drug treatment schedules." (PMID 34621046, 2021). "Exosomes contain large dsDNA fragments spanning multiple genomic regions and harbor EGFR (T790M and L858R) 82 and BRAF (V600E) 83 gene mutations, proposing the possibility of tracing these mutations in plasma exosomes of NSCLC and/or melanoma patients through liquid biopsy." (PMID 34234872, 2021). "SIJ1777 significantly suppresses the proliferation of melanoma cells in vitro, regardless of BRAF mutation status." (PMID 33917428, 2021). "In other words, it means uncertainty about whether the prognosis will be good (bona fide Spitz, with tyrosine kinase fusion), or conversely, the evolution could be more aggressive and eventually lethal (BRAF or NRAS melanoma)." (PMID 34449585, 2021). "In addition, the synergistically abolishing effect of Octpep-1 with the ERKi is in accordance with the current literature stating that MAPK is stimulated in BRAF melanoma." (PMID 33672955, 2021). "As expected, bilirubin reversed vemurafenib-induced apoptosis in BRAF V600 mutant melanoma cells." (PMID 34222023, 2021). "In this paper the authors propose that G4 stabilization might be relevant in the context of resistance to targeted therapies of BRAF mutant melanomas." (PMID 33632214, 2021). "It is a valuable UV-independent genetic model for the development of melanoma, with causative somatic pathogenic variants in NRAS in 70%,2,3 and BRAF in 7%,3,4 with the remainder as yet unknown." (PMID 34145395, 2021). "Our finding showed for the first time that PLA1A with the highest sensitivity, specificity, and AUC could be used as a single indispensable marker for diagnosis, screening, and prognosis in BRAF-MUT advanced melanoma." (PMID 33723350, 2021). "BRAF mutant melanoma cells, when compared to NRAS mutant ones, showed higher expression of Sema6A." (PMID 33858502, 2021). "In patients with NSCLC, the prognostic impact of non-V600 mutations is not consistent across reports, while in patients with melanoma, there was no significant survival difference between non-V600 mutations, V600 BRAF-mutation, and BRAF wild-type." (PMID 33842313, 2021). "These experiments were performed in A375 melanoma cells, which are sensitive to BRAF inhibitors." (PMID 33431809, 2021). "Cyclin dependent kinase 4/6 inhibitors (CDK4/6i) may also play a role in enhancing duration of response in combination with BRAF-MEKi via blockade of the cell cycle and exerting immunomodulatory effects on melanoma." (PMID 34944961, 2021). "We next investigated whether replacement or inhibition of miR-181a/b could affect the proliferation of two melanoma cell lines sensitive (A375, M14) or resistant to BRAF inhibitors (A375-BIR, M14-BIR)." (PMID 33670365, 2021). "It has been shown that TS-fibroblasts mediate resistance upon BRAF inhibition in melanoma." (PMID 33669949, 2021).
melanoma (continued). "Also, forced overexpression of SIRT3 in BRAF-mutant Hs294T-xenografted mouse model promoted tumorigenesis in melanoma." (PMID 33937086, 2021). "In patients resistant to BRAF and MEK inhibitors, GRP78 upregulation and ATF4 phosphorylation were found, suggesting that ER translocation of the MAPK pathway causes treatment resistance in BRAF-mutant melanoma." (PMID 34804979, 2021). "Additionally, we recently reported Rho/MRTF pathway activation in a subset of BRAFBRAFV600 mutant melanoma cell lines that are resistant to BRAF/MEK inhibitors." (PMID 33921974, 2021). "In the ongoing phase 3 DREAMseq trial, patients with unresectable stage III or IV BRAFV600-mutant melanoma receive either BRAF/MEK inhibitor therapy with dabrafenib and trametinib and switch after progression to ICI therapy with ipilimumab and nivolumab, or the other way around." (PMID 33804800, 2021). "Additionally, the subset of the BRAF mutated melanoma cohort of the cancer genome atlas (TCGA) harboring an EZH2 silent mutation, showed a highly significant enforced miR-129-5p expression compared to BRAF mutated melanoma patients with EZH2 wildtype." (PMID 34063443, 2021). "Therefore, we evaluated an additional model which only included NRAS wild type lesions in patients with BRAF-wt melanoma (model 3)." (PMID 33915880, 2021). "In BRAFV600E-mutated melanoma cells, upregulated OXPHOS and mitochondrial respiration, increased ROS levels, and attenuated glucose metabolism are associated with drug resistance to BRAF inhibitors." (PMID 34066184, 2021). "It has been shown that BRAF mutation in melanoma could increase MCL-1 expression, suggesting that activating BRAF mutations would confer resistance to apoptosis." (PMID 33917026, 2021). "While the major drivers of melanoma initiation, including activation of NRAS/BRAF and loss of PTEN or CDKN2A, have been identified, the role of key transcription factors that impose altered transcriptional states in response to deregulated signaling is not well understood." (PMID 34140478, 2021). "Polymerase Chain Reaction (PCR) and Sanger sequencing techniques were performed to identify the mutational status of BRAF, NRAS, KRAS, NF1, KIT, PDGFRA and SF3B1 on 19 melanomas of the female genital tract, paired with 25 cutaneous melanomas, 18 acral melanomas and 11 melanomas of nasal cavity." (PMID 34102999, 2021). "The high frequency of CDK4/6 pathway activation in cancer more broadly has led to the development of CDK4/6 inhibitors, such as palbociclib, ribociclib and abemaciclib, and the therapeutic effects of palbociclib have been studied in the context of BRAF inhibitor resistance in melanoma." (PMID 33572972, 2021). "The apoptotic efficacy of PI3K inhibitor Alpelisib (BYL719) has also been shown to increase under BRAF-inhibited conditions, suggesting that prolonged BRAF inhibition may lead to increased efficacy of PI3K inhibitors in treating melanoma." (PMID 33807778, 2021). "Likewise, in the context of targeted therapies, increased oxidative stress is observed in melanoma cells resistant to BRAF inhibition, while autophagy supports drug resistance against EGFR-targeted therapies in EGFR-driven cancer cells." (PMID 33807785, 2021).
melanoma (continued). "It is worth noting that melanoma without mutated BRAF was not treated by either vemurafenib or dabrafenib." (PMID 34638829, 2021). "Continuing, the relationship between the presence of circulating tumor DNA and plasma levels of kinase inhibitors in patients with advanced BRAF(V600) mutant melanoma is being investigated in a study entitled “Therapeutic Drug Monitoring of BRAF-mutated Advanced Melanoma”." (PMID 34575876, 2021). "RAC1 P29S confers resistance to BRAF inhibitors through the SRF/MRTF signaling pathway, indicating that targeted SRF/MRTF therapy may overcome BRAF inhibitor resistance in melanoma patients with RAC1P29S mutations." (PMID 34804979, 2021). "However, little information is available in the form of real-world data on treatment patterns and clinical outcomes for patients with advanced BRAF V600 mutant melanoma." (PMID 34064013, 2021). "The BRAF gene can be also amplified in a small subset of melanomas." (PMID 34063141, 2021). "The nevogenic tumors had a higher frequency of BRAF mutations than the CSD melanomas, although the difference was not statistically significant (46/82, 56.1% vs. 14/37, 37.8%; p = 0.077)." (PMID 34680367, 2021). "Combined treatment with Usp9x and mutant BRAF inhibitors fully suppressed melanoma growth in vivo." (PMID 33613844, 2021). "The BRAF biomarker and prognostic scores, such as the melanoma molGPA, could be used as tools in treatment decision making." (PMID 33993415, 2021). "Based on these molecular characteristics of the melanoma, specific BRAF (V600E) ATP-competitive inhibitors, such as vemurafenib or dabrafenib have been developed and have shown remarkable clinical efficacy in BRAF(V600E) melanoma tumors." (PMID 33804655, 2021). "BRAF, as a component in MAPK/ERK signal pathway, is commonly found to mutate in quite a few malignancies, and BRAF inhibitors were discovered to be useful in increasing TILs in mouse and human melanoma." (PMID 34766142, 2021). "Like most melanomas, most nevi are clonal proliferations of BRAF V600E/K mutant melanocytes." (PMID 33539342, 2021). "Even the well-known driver mutation on BRAF gene (e.g. V599E) was only present in 66% but not all of malignant melanomas." (PMID 34097054, 2021). "Studies have shown that OXPHOS mediates BRAF-mutant melanoma treatment evasion." (PMID 33810045, 2021). "BRAF mutations have been found in melanoma (80–90%), thyroid cancer (60%), colorectal cancer (40%), non-small cell lung cancer (6%), pancreatic cancer (90%), and others." (PMID 33420213, 2021). "Mutations in BRAF, NRAS, NF1, and KIT have been all implicated as melanoma drivers." (PMID 33619278, 2021). "The cytoplasmic intergenic lncRNA MIRAT (MAPK inhibitor resistance-associated transcript), instead, has been described as significantly over-expressed in melanoma cells, carrying NRAS or BRAF mutations, resistant to small molecule inhibitors of the MAPK cascade." (PMID 33503876, 2021). "Furthermore, BRAFi resistant BRAFV600E melanoma cells can even become dependent on the BRAF inhibitor for proliferation." (PMID 34066966, 2021). "In melanoma, key oncogenic drivers, such as BRAF and NRAS, have been well defined." (PMID 34140478, 2021). "Even though dermoscopy cannot replace molecular methods and histopathology in determining BRAF mutational status and SLN status, it could be a useful additional diagnostic tool in predicting these melanoma features." (PMID 33954019, 2021). "The study of mutations on BRAF is of interest because Vemurafenib as a potent inhibitor of mutated BRAF has great antitumor effects against melanoma with the BRAF V600E mutation but not against cells with other mutations." (PMID 34567185, 2021).
melanoma (continued). "A pooled analysis including KEYNOTE-001, KEYNOTE-002, and KEYNOTE-006 study endorses the use of pembrolizumab for treatment of advanced melanoma independent of BRAF V600 mutation status or previous treatment with BRAF inhibitor with or without MEK inhibitor." (PMID 34804979, 2021). "Hence, downregulation of MAPK signaling by anti-EGFR antibodies, or inhibitors of EGFR, MEK, and BRAF enhances the expression of HLA-I in several types of tumors, such as lung cancer, melanoma, and head and neck squamous cell cancer." (PMID 34458148, 2021). "Previously it was shown that in BRAF mutant melanoma cells, PLX treatment led to a decrease in the protein levels of N-cadherin and MMP2 among other EMT-related markers; however, when resistance to PLX developed, there was a significant increase in the expression of these proteins." (PMID 33810045, 2021). "Our current findings, along with our previous discovery that the AXL/AKT axis mediates resistance to BRAF inhibition in melanoma with wild-type PTEN, provide new insights toward a strategy for combating BRAF inhibition-acquired resistance in BRAF mutant melanoma with different PTEN statuses." (PMID 34282258, 2021). "Similarly, HGF activation of the MET signaling pathway can decrease the response of BRAF-mutant melanomas to BRAF inhibition." (PMID 34071428, 2021). "On the other hand, we also observed patients as well as cell lines that exhibited decreased CD73 expression following RAS‐MAPK‐targeted treatment, supporting recent studies showing that melanoma patients experienced decreased CD73 expression during BRAF treatment." (PMID 34165921, 2021). "If the strategy of combined targeting of BRAFV600E signaling plus autophagy proves to be effective in BRAF-driven melanoma, this could open a therapeutic avenue for other BRAF-driven cancers, such as lung, colorectal, thyroid, and hairy cell leukemia." (PMID 34298710, 2021). "In addition, we also evaluated the effect of eIF3a on the antitumor activity of dabrafenib, another BRAF inhibitor approved by the FDA to treat melanoma." (PMID 34512348, 2021). "Moreover BAY 87-2243 was able to reduce tumor growth in both BRAF mutant melanoma mouse xenografts and patient-derived melanoma mouse models." (PMID 34426760, 2021). "Additionally, BRAF- and NRAS-mutated melanoma cells exhibit elevated utilization of this amino acid as a substrate for fatty acid biosynthesis." (PMID 33918883, 2021). "The application of MEK-targeted agent has been then extended to melanomas lacking BRAF mutation, since that some other populations of melanomas are also dependent on MAPK signal pathway to survive and growth." (PMID 34924562, 2021). "Previous genome-scale sequencing studies have identified mutations in a number of genes involved in the initiation and progression of melanoma, including BRAF (50%), NRAS (20–30%), neurofibromin 1 (NF1) (10–15%), and cyclin-dependent kinase inhibitor 2A (CDKN2A) (20–40%)." (PMID 34771678, 2021). "In addition to immune checkpoint therapy, some commonly used melanoma-targeting drugs, including BRAF and MEK inhibitors, also affect the immune microenvironment through pyroptosis." (PMID 34327145, 2021). "Finally, the upregulation of fatty acid oxidation is one of the requirements for BRAF-mutant melanoma cells to avoid apoptosis under the metabolic stress induced by MAPK inhibitors prior to the emergence of drug resistance." (PMID 33430277, 2021). "Similarly, a study in BRAF mutant melanoma indicated that c-Myc is reactivated at the gene and protein levels in tumor tissues and cell lines with acquired resistance to BRAF inhibitors." (PMID 34201061, 2021).
melanoma (continued). "Hence, there is still the unmet medical need for more efficient targeted approaches against advanced or metastatic BRAF(V600E) melanoma." (PMID 33672955, 2021). "In a phase 1 study using trametinib in advanced melanomas, trametinib did not demonstrate efficacy in the majority of patients with BRAF/NRAS wild-types, but one patient with an NF1 mutation had a stable disease." (PMID 34831002, 2021). "In this study, we reviewed all cases of patients treated with SRS for melanoma metastases in an effort to quantify the degree to which BRAF/MEK targeted therapy and immunotherapy show an extracranial response with the development of intracranial metastatic diseases." (PMID 33824801, 2021). "In particular, recent evidence supports the concept that combined BRAF-MEK inhibitors could enhance recognition of melanoma cells by the immune system, thus favoring the activity of immune-checkpoints inhibitors." (PMID 34683910, 2021). "In addition, Octpep-1 combined with rapamycin (mTORC1 inhibitor) or LY3214996 (ERK1/2 inhibitor) augmented the cytotoxicity against BRAF(V600E) melanoma cells in comparison with the inhibitors or Octpep-1 alone." (PMID 33672955, 2021). "Melanomas are currently subjected to BRAF and, in some instances, KIT genetic analysis." (PMID 34681592, 2021). "Recent work has shown that inhibition of wild-type KRAS in BRAF-mutant melanoma can be a potential strategy since inhibition of KRAS works synergistically with BRAF inhibition to reduce the proliferation and induce apoptosis independent of BRAF mutation status." (PMID 33801965, 2021). "However, the combination of a MEK inhibitor with a BRAF inhibitor can improve antileukemic efficacy and reduce the frequency of secondary cutaneous malignancies in melanoma and HCL patients." (PMID 33216198, 2021). "To understand whether the ECM and focal adhesion genes affected upon MITF loss overlap with the gene signature of melanoma cells that have been treated with BRAF inhibitors, we used single-cell RNA-sequencing data of human melanoma xenografts." (PMID 33438577, 2021). "Moreover, competitive kinase inhibitors, are directed towards the increased activity of BRAF induced by a specific alteration (V600E/K) in the BRAF -gene in patients diagnosed with malignant melanoma." (PMID 33916923, 2021). "Along those lines, it has been shown that MAPK–inhibitors used for the treatment of BRAF-mutant melanomas induce TNF-α production by a macrophage population that triggers the expression of MITF (microphthalmia transcription factor), resulting in the resistance of cancer cells to MAPK inhibitors." (PMID 33803675, 2021). "Furthermore, a recent study reported that the expression of BOP1 protein was downregulated in melanoma patients, and that BOP1 loss was related to BRAF kinase resistance." (PMID 34603446, 2021). "In this study, we wondered whether bilirubin may influence the clinical outcome of patients with BRAF mutant melanoma." (PMID 34222023, 2021). "Thus, combined therapy is being implemented for melanoma patients, targeting different pathways simultaneously, such as BRAF and MEK inhibition." (PMID 33669949, 2021). "Furthermore, changes in CTC numbers were assessed in five patients with stage IV melanoma at four time points during BRAF/MEK inhibitor treatment, and the BRAF genotype was analyzed in CTCs isolated from one patient." (PMID 33731038, 2021). "Interestingly, BRAF inhibitors induce reactive oxygen species (ROS) in melanoma cells, therefore, the aim of this study was to investigate a possible interplay between HGF/c-met and ROS sources, such as NADPH oxidases (Nox)." (PMID 33451139, 2021). "In the COSMIC database, no data are available for penile and scrotum melanomas, while vulvar lesions show 10.5% of BRAF mutations (other than V600E)." (PMID 33525348, 2021).